SEMA3A (semaphorin 3A)
Diseases named in the same sentence as SEMA3A in open-access papers (continued):
Sharing a sentence is not in itself a finding about the gene and the disease.
emphysema (1 paper, 2011). "During late embryonic development, maturation and/or differentiation defects of distal lung epithelium were observed in Sema3A-/- mice, and the rare Sema3A-/- mice surviving to postnatal day 14 (P14) or beyond exhibited profound developmental emphysema." (PMID 22096573, 2011). "Because dysregulation of lung structural cell proliferation and death have been shown to play an important role in the pathogenesis of emphysema in experimental models, Sema3A signals may therefore also be important determinants of plasticity following lung injury and alveolar remodeling." (PMID 22096573, 2011).
gastric tumour (1 paper, 2018). "Decreased expression of SEMA3A was observed in gastric tumour tissue in comparison to a control." (PMID 29649113, 2018).
Hepatic steatosis (1 paper, 2024). Steatosis is a term used to denote lipid accumulation within hepatocytes. "More specifically, iECSema3a mice and Cdh5-CreERT2 controls (abbreviated as iECwt) were fed an HFD for 10 weeks to induce hepatic steatosis, followed by injections with tamoxifen to efficiently delete the Sema3a allele." (PMID 39196233, 2024). "These experiments show that deletion of endothelial Sema3a in adult DIO mice reduces early hepatic steatosis and improves VLDL secretion from the liver." (PMID 39196233, 2024). "We next studied the degree of hepatic steatosis in liver tissue from DIO Sema3a+/− and control mice after feeding them an HFD for 20 weeks." (PMID 39196233, 2024). "We next assessed whether reduction of SEMA3A signaling in mice with manifested hepatic steatosis could reduce hepatic fat content." (PMID 39196233, 2024). "In conclusion, mouse and human LSECs express Sema3a/SEMA3A and its expression is higher in LSECs from mice with hepatic steatosis compared to those without." (PMID 39196233, 2024).
Hirschsprung disease (1 paper, 2020). Hirschsprung disease (HSCR) is a congenital intestinal motility disorder that is characterized by signs of intestinal obstruction due to the presence of an aganglionic segment of variable extent in the terminal part of the colon. "Interestingly, changes in Sema3A expression have been described in the colon of some patients with Hirschsprung disease (HSCR) and rare coding and non-coding deleterious variants of Sema3A have been identified in HSCR cohorts." (PMID 32934297, 2020). "Here, we examined the role of Semaphorin 3A (Sema3A) on ENS maturation and its potential implication in Hirschsprung disease (HSCR), a developmental disorder of the ENS with impaired colonic motility." (PMID 32934297, 2020).
Hypertension (1 paper, 2023). The presence of chronic increased pressure in the systemic arterial system. "Consistent with these mouse data, Sema3A expression was significantly higher in the hypertrophic hearts and plasma of patients, in the serum of patients with hypertension‐related cardiac dysfunction, and in the hearts of SHRs compared to the corresponding controls." (PMID 37310417, 2023).
Hypoglycemia (1 paper, 2021). A decreased concentration of glucose in the blood. "Since secreted semaphorins (SEMA3 class) generally require NRPs as obligate co-receptors to interact with their surface receptors, it is likely that sNRP1 would also interact with SEMA3A in obese T2D in response to hypoglycemia." (PMID 34248841, 2021). "Here we report the levels of soluble neuropilin-1 (sNRP1), NRP1 proteolytic enzyme ADAM9 and NRP1 ligands, VEGF and SEMA3A, in response to insulin-induced hypoglycemia in obese patients with T2D." (PMID 34248841, 2021). "Soluble isoforms of NRP1 (sNRP1) also exist without transmembrane or cytoplasmic domains, expressing only the extracellular domains which allow them to bind NRP1 ligands; therefore, the plasma levels of NRP1 ligands (VEGFA and SEMA3A) were determined in response to insulin-induced hypoglycemia." (PMID 34248841, 2021).
infarction (1 paper, 2013). A localised pathological necrosis of tissue resulting from obstruction of the blood supply usually by a thrombus, an embolus, or vascular torsion. "In this study, we observed the effect of myocardial overexpression of sema3a on after infarction sympathetic reinnervation and the inducibility of VT by PES in a rat MI model." (PMID 23711091, 2013). "Consistent with the notion that the nerve sprouting was augmented at the MI border zone 30–32, our results detected excessive sympathetic reinnervation after infarction at the MI border zone, and this process could be inhibited by myocardial Sema3a overexpression in this MI model." (PMID 23711091, 2013).
invasive breast ductal carcinoma (1 paper, 2024). "A high expression of PLXNA2 has been associated with invasive breast ductal carcinoma compared to benign tumours, while in ECs, the co-receptor acts as an antiangiogenic and pro-permeability factor through semaphorin 3A signalling." (PMID 38203852, 2024).
ischemia reperfusion injury (1 paper, 2022). Adverse functional, metabolic, or structural changes in ischemic tissues resulting from the restoration of blood flow to the tissue (reperfusion), including swelling; hemorrhage; necrosis; and damage from free radicals. "Moreover, retinal ganglion cells (RGCs) also control retinal vessel growth through G protein-coupled receptor-91 (GPR91) and neuronal guidance cue semaphorin 3 A (SEMA3A), and capillary degeneration in mice induced with ischemia-reperfusion injury." (PMID 36420952, 2022).
joint diseases (1 paper, 2016). "This “osteoprotective” effect of Sema3A suggests that modulation of the Sema3A-PlxnA signal may be of potential utility in the treatment of various bone and joint diseases." (PMID 27258772, 2016).
left ventricular hypertrophy (1 paper, 2023). Enlargement of the LEFT VENTRICLE of the heart. "Furthermore, echocardiographic measurements showed improvement in left ventricular hypertrophy and diastolic function when Sema3A was knocked down in MiVECs upon pressure overload." (PMID 37310417, 2023).
liver cancer (1 paper, 2016). An epithelial or non-epithelial malignant neoplasm that arises from the liver. "We also investigated the effect of Sema3A using an orthotopic nude mouse liver cancer model." (PMID 27351132, 2016).
macular oedema (1 paper, 2016). "This is an important consideration, given the finding that SEMA3A induces retinal oedema in a mouse model of PDR and the observed upregulation of SEMA3A in the retina during the early hyperglycaemic phase in diabetic patients with macular oedema (see Sections 3.3, 3.4)." (PMID 26923176, 2016).
memory (1 paper, 2022). The activities involved in the mental information processing system that receives (registers), modifies, stores, and retrieves informational stimuli. "Finally, we identified the cognition-related gene Sema3A, which may play a significant role in the spatial learning and memory deficits associated with REM sleep deprivation." (PMID 36159327, 2022).
metabolic syndrome (1 paper, 2022). A cluster of metabolic risk factors for CARDIOVASCULAR DISEASES and TYPE 2 DIABETES MELLITUS. "In metabolic syndrome, SEMA3A was shown to have an inhibitory role in adipogenesis." (PMID 36551769, 2022).
metastasis (1 paper, 2016). The spread or migration of cancer cells from one part of the body (where they first appeared) to another. "Moreover, the expression of SEMA3A was correlated with smaller tumor size and reduced local lymph node metastasis." (PMID 26755661, 2016).
metastatic disease (1 paper, 2022). "Restored expression of SEMA3A resulted in the normalization of the tumor vasculature, impairment of metastatic disease progression, and sensitization of immunotherapy." (PMID 36143975, 2022).
monoclonal gammopathy of undetermined significance (1 paper, 2018). "Semaphorin 3A (Sema3A) is implicated as an antiangiogenic inducer in monoclonal gammopathies pathophysiology." (PMID 29748532, 2018). "More specifically, loss of Sema3A favors the angiogenic effect of Vascular Endothelial Growth Factor165 and may be involved in the angiogenic transition from monoclonal gammopathy of undetermined significance to MM5." (PMID 29748532, 2018).
Myocardial fibrosis (1 paper, 2023). "However, a mechanistic explanation for the mediation of myocardial fibrosis by Sema3A‐positive sEVs in this study has not been established." (PMID 37310417, 2023).
nasopharyngeal carcinoma (1 paper, 2020). A carcinoma arising from the nasopharyngeal epithelium. "This study aimed to analyze the association of Sema3A with the clinical features of nasopharyngeal carcinoma (NPC), an Epstein–Barr virus-associated carcinoma, and the Epstein–Barr virus primary oncogene latent membrane protein 1 (LMP1)." (PMID 32192122, 2020).
nephrotic syndrome (1 paper, 2023). A collection of symptoms that include severe edema, proteinuria, and hypoalbuminemia; it is indicative of renal dysfunction. "Several reports have indicated the potential use of inhibitory drugs of SEMA3A signaling against kidney diseases, and also identified SEMA3A expression as a potential biomarker for the early detection and prognosis of AKI and the relapse of nephrotic syndromes." (PMID 37835781, 2023).
oral cavity cancer (1 paper, 2024). A primary or metastatic malignant neoplasm involving the oral cavity. "SEMA3A, regulated by the Wnt/β‐catenin‐dependent pathway, has been implicated in oral cavity cancer including OSCC." (PMID 39177014, 2024).
oral squamous cell carcinoma (1 paper, 2024). "Previous studies have supported a tumor‐suppressive role of semaphorin 3A (SEMA3A) in several tumors including oral squamous cell carcinoma (OSCC)." (PMID 39177014, 2024).
portal hypertension (1 paper, 2014). Increased blood pressure in the portal venous system. "Simultaneously, the increased ROCK expression points out to an activated process of axon retraction in portal hypertension, either from Sema3A signaling or from caspase-dependent apoptosis." (PMID 24400086, 2014). "The increase in Sema3A might also be necessary to redirect axons to innervate newly formed blood vessels from preexisting vasculature during portal hypertension." (PMID 24400086, 2014).
renal dysfunction (1 paper, 2014). "The baseline creatinine difference before surgery suggests that AKI patients did not harbor any renal dysfunction prior to transplantation, which was further supported by the similar low basal levels of NGAL and sema3A in both groups." (PMID 25289643, 2014).
small cell lung carcinoma (1 paper, 2019). Small cell lung cancer (SCLC) is a highly aggressive malignant neoplasm, accounting for 10-15% of lung cancer cases, characterized byrapid growth, and early metastasis. "The first evidence of the involvement of semaphorins in tumorigenesis was provided by the isolation of semaphorin 3A (Sema3A) and Sema3F genes in the 3p21 chromosomal region, where a deletion was found in the majority of small-cell lung cancers." (PMID 31052281, 2019).
urothelial carcinoma (1 paper, 2021). A malignant neoplasm derived from the transitional epithelium of the urinary tract (urinary bladder, ureter, urethra, or renal pelvis). "In a previous study by our team, we showed that Sema3A is overexpressed in patients with urothelial carcinoma (UC)." (PMID 33546237, 2021).
vascular malformation (1 paper, 2009). A non-neoplastic disorder that is the result of defects of vascular morphogenesis. "Defects of developing blood vessels caused by Nrp1 gene knockdown in mice are different from vascular malformations displayed by mice lacking either SEMA3A or VEGF-A165 (Vegf-a120/120 mice)." (PMID 19175293, 2009).
Waldenstrom macroglobulinemia (1 paper, 2019). "Besides, some genes are involved in osteoblastogenesis (SEMA3A, BICC1, CHRLD1, and ZNF521) and HAS1 is involved in Waldenstrom’s macroglobulinemia, a post-follicular B-cell lymphoproliferative disorder also associated with M-protein production (IgM)." (PMID 30705326, 2019).
xerosis (1 paper, 2021). "Therefore, we consider Sema3A as a key therapeutic target for improving histamine-resistant itch in AD and xerosis." (PMID 33905439, 2021).
tumor (165 papers, 2008 to 2026). "For instance, Sema3A, Sema4C, and Sema4D promote tumor progression by attracting tumor-associated macrophages." (PMID 40103807, 2025). "SEMA3A can cause immune suppression by affecting tumor-specific CD8+ T cell filamentous actin, which results in inhibition of immune synapse formation and motility." (PMID 40430095, 2025). "In contrast, cytoskeletal regulator SEMA3A downregulation is associated with enhanced tumor angiogenesis and progression in solid tumors." (PMID 39416100, 2025). "Third, in ccRCC patients CD8+ TILs were preferentially found in SEMA3A rich regions and beside Sema3A rich blood vessels, reminiscent of how tumor-associated macrophages can be entrapped within SEMA3A rich hypoxic regions." (PMID 38609390, 2024). "NRP-1 has been detected on tissue-resident macrophages as well as on tumor-associated macrophages (TAMs), where it plays a critical role in their migration to the tumor hypoxic niche in response to SEMA3A." (PMID 39857591, 2024). "Cluster c7 expressed high level of Tead4, a key mediator of the Hippo signaling pathway, implicated in the promotion of epithelial-mesenchymal transition and metastatic cascade, and the axon guidance cue, Sema3a, implicated in tumor angiogenesis." (PMID 39457009, 2024). "Sema3A is believed to be closely associated with tumor progression and acts as a potent suppressor of tumor angiogenesis and VEGF function at various stages of cancer." (PMID 38139064, 2023). "Plexin-A4 (or plexin-A1) in a complex with NRP-1 can transduce sema3A attractive signals involving VEGFR1 for tumor-associated macrophages after hypoxia induction." (PMID 37627074, 2023). "For instance, Sema3A, Sema4C, and Sema4D have been found to promote tumor progression by enrichment of tumor-associated macrophages in TME." (PMID 35155237, 2022). "Upon entry into the hypoxic niche, Nrp1 is downregulated, thereby reducing Sema3A-mediated migratory responses, and trapping the tumor associated macrophages in the hypoxic niche." (PMID 36203599, 2022). "According to the MEXPRESS database, the methylation of HNRNPAB/PLAUR/SEMA3A was associated with several clinical factors including ‘new tumour event after initial treatment’ and ‘tumour stage’." (PMID 36091160, 2022). "The group found that hypoxia induced Sema3A-mediated chemoattraction for tumor-associated macrophages through the VEGFR/Nrp1/PlexinA1/PlexinA4 receptor complex." (PMID 36203599, 2022). "Investigating the spatial positioning of the tumor associated macrophages with knock-out and WT macrophages, the group reported that Sema3A drives tumor associated macrophage trafficking into areas of hypoxia in a Nrp1-dependent manner." (PMID 36203599, 2022). "The pathway analysis showed the involvement of the selected proteins in biological processes directly associated with tumor evolution (SEMA3A, BMP6, MDK), hepatitis viral infection (ISG15), or physiological liver functions (PLTP)." (PMID 35008303, 2021). "More recently, the class 3 semaphorin SEMA3A was shown to act as an attractant for tumor-associated macrophages (TAMs), regulating their localization and retention within hypoxic tumor areas." (PMID 32191647, 2020). "SEMA3A also acts as a chemoattractant for macrophages and promotes tumor-associated macrophage (TAM) infiltration." (PMID 31205625, 2019). "Binding of VEGF-A to NRP1 favors growth and metastasis of solid tumors, whereas, binding of SEMA3A is generally associated with less migration and invasion of tumor cells and thus better prognosis." (PMID 30717262, 2019). "Nevertheless, one of the mechanisms of tumor suppression by Sema3A has been recently demonstrated by Wallerius and associates." (PMID 30134791, 2018). "Sema3A has not previously been ascribed a role in resolving inflammation, though Sema3A has been shown to limit the recruitment of tumor-associated macrophages, restricting angiogenesis and restoring antitumor immunity." (PMID 28540528, 2017).
tumor (continued). "We observed a significant correlation between the expression of Sema3A and the number of intratumoral macrophages, especially M2 tumor-associated macrophages (CD163+ macrophages)." (PMID 27351132, 2016). "Semaphorin 3A also acted as a chemoattractant involved in direct recruitment of macrophages in vitro, and facilitated tumor-associated macrophage (TAM) infiltration in vivo." (PMID 27351132, 2016). "Sema3A expression was strongly associated with tumor recurrence and predicted a poorer post-surgical prognosis for patients." (PMID 27351132, 2016). "An important recent study found that hypoxia-induced Semaphorin 3A acts as an attractant for tumor-associated macrophages and further showed that prevention of hypoxic migration abated macrophage immune suppression and promoted anti-tumor immunity." (PMID 26343197, 2015). "PNCA, as an important indicator of tumor proliferation index, is more strongly associated with semaphorin-3A and MMP-14." (PMID 24765144, 2014). "While Sema3A, 3B, and 3F demonstrate antitumorigenic or antiangiogenic properties in various cancer types, other members are implicated in the promotion of tumor progression." (PMID 23050142, 2012). "We also examined the effects of sema3A and sema3F expression on the concentration of tumor associated blood vessels in MCF-7 cells." (PMID 18818766, 2008). "Expression of sema3A in these cells significantly reduced the concentration of tumor associated blood vessels." (PMID 18818766, 2008). "The molecular mechanisms underlying the anti-tumor effects of SEMA3A are being extensively studied, the antiangiogenic factor SEMA3A may be capable of inhibiting the proangiogenic activity of vascular endothelial growth factor (VEGF)." (PMID 32842711, 2020). "It has been linked to a tumor-promoting environment upon interaction with semaphorin 3A (Sema3A)." (PMID 33266104, 2020). "Furthermore, Sema3A directly decreases focal adhesions, induces cancer cell invasion in vitro, and modulates tumor-associated macrophages." (PMID 32192122, 2020). "It seems possible that lower SEMA3A expression in poorly differentiated tumours and metastatic tumour tissue may be associated with drug resistance; this possibility, however, requires further investigation." (PMID 29649113, 2018). "First, we showed that starvation medium from cultured SSC-9 with Sema3A overexpression significantly inhibited tubule formation in endothelial cells, (P < 0.01), which indicated Sema3A inhibited angiogenesis caused by tumor growth factors secreted from SSC-9." (PMID 28683823, 2017). "Moreover, adenovirus transfection and recombinant SEMA3A protein approaches were used to identify the multiple tumor suppressor roles of SEMA3A and the potential underlying mechanisms in vitro." (PMID 26755661, 2016). "SEMA3A-induced tumor vessel normalization might be indirectly caused by SEMA3A-mediated recruitment of a subset of NRP1-expressing monocytes that secrete several factors involved in vessel maturation." (PMID 24521511, 2014). "In fact, SEMA3A has been implicated as a tumour suppressor in other types of cancer." (PMID 22926477, 2012). "The association between SEMA3 gene expressions and tumor stemness score as well as with the drug sensitivity score indicated that SEMA3A, SEMA3C, and SEMA3F may mainly play tumor promotor roles during tumorigenesis as they are positively associated with tumor stemness and drug resistence scores." (PMID 32241267, 2020). "However, SEMA3A over-expression in several cancer types may promote the dispersal of tumor cells and be associated with metastasis and shorter survival." (PMID 26755661, 2016). "We showed that BA inhibits the growth of tumour cells by inducing the SEMA3A/PLXNA1/NRP1 pathway and prevents cell growth by inducing oxidative damage and activating apoptosis through excessive ROS generation." (PMID 40318008, 2025).